SLURP1 (secreted LY6/PLAUR domain containing 1)
Description:
Has an antitumor activity. Was found to be a marker of late differentiation of the skin. Implicated in maintaining the physiological and structural integrity of the keratinocyte layers of the skin. In vitro down-regulates keratinocyte proliferation; the function may involve the proposed role as modulator of nicotinic acetylcholine receptors (nAChRs) activity. In vitro inhibits alpha-7-dependent nAChR currents in an allosteric manner. In T cells may be involved in regulation of intracellular Ca(2+) signaling. Seems to have an immunomodulatory function in the cornea (By similarity). The function may implicate a possible role as a scavenger receptor for PLAU thereby blocking PLAU-dependent functions of PLAUR such as in cell migration and proliferation.
Synonyms: ANUP; ARS; MDM; ArsB; LY6LS; LY6-MT
Tractability: Antibody: UniProt places it where antibodies can reach, with high confidence; UniProt predicts a signal peptide or a membrane-spanning region; its Gene Ontology location is reachable by antibodies, with medium confidence.
Gene: Protein-coding gene on chromosome 8 (142,740,949 to 142,742,406, reverse strand). Ensembl gene ENSG00000126233.
Subcellular location: Secreted
Gene Ontology:
Molecular function: acetylcholine receptor activator activity; protein binding; cytokine activity
Biological process: negative regulation of cell migration; negative regulation of cell population proliferation; urokinase plasminogen activator signaling pathway; cell activation; cell adhesion
Cellular component: extracellular exosome; extracellular region
Genetic constraint (gnomAD): Loss-of-function variants: 4 observed, 8.87 expected, observed/expected ratio (o/e) 0.45, 90% interval 0.22 to 1.03. That is too few expected variants to judge how well the gene tolerates losing a copy. Missense variants: 111 observed, 136.89 expected, observed/expected ratio (o/e) 0.81, 90% interval 0.69 to 0.95. Synonymous variants: 59 observed, 54.54 expected, observed/expected ratio (o/e) 1.08, 90% interval 0.88 to 1.34.
Homologues: Orthologues: chimpanzee SLURP1 (100% identical), macaque SLURP1 (90% identical), rat Slurp1 (70% identical), mouse Slurp1 (68% identical), dog SLURP1 (65% identical), guinea pig SLURP1 (58% identical). Paralogues in human: LYPD2 (41% identical), CD59 (29% identical), LYPD1 (25% identical).
Diseases named in the same sentence as SLURP1 in open-access papers:
SLURP1 is named in the same sentence as 75 diseases in open-access papers, as found by Europe PMC text mining. Sharing a sentence is not in itself a finding about the gene and the disease. The quoted sentences say what the papers report.
Palmoplantar keratoderma (10 papers, 2011 to 2023). Abnormal thickening of the skin of the palms of the hands and the soles of the feet. "Mal de Meleda is an autosomal recessive palmoplantar keratoderma, with SLURP1 identified as the pathogenic gene responsible." (PMID 37393290, 2023). "Interestingly, mutations in the gene encoding SLURP-1 have been detected in patients with Mal de Meleda (MdM), a rare autosomal recessive skin disorder characterized by transgressive palmoplantar keratoderma." (PMID 34202925, 2021). "Moreover, SLURP1-deficient mice show severe palmoplantar keratoderma characterized by increased proliferation of keratinocytes and water barrier defects." (PMID 34202925, 2021). "Mutations in the gene encoding SLURP-1 were detected in patients with Mal de Meleda, a rare autosomal recessive skin disorder characterized by transgressive palmoplantar keratoderma; some mutations located in loops I and II and the head of SLURP-1 may potentially drive the disease." (PMID 38069271, 2023). "The discovery of mutations in the gene encoding SLURP-1 in Mal de Meleda (MdM) patients with a characteristic transgressive palmoplantar keratoderma is drawing major research attention to the capacity of SLURP-1 to serve as an epithelial growth modulator." (PMID 28932225, 2017). "Slurp1−/− mice develop signs of palmoplantar keratoderma including elevated keratinocyte proliferation, accumulation of lipid droplets in the stratum corneum, and defective epidermal barrier function reminiscent of mal de Meleda." (PMID 27098205, 2016). "Slurp2−/− mice also develop signs of palmoplantar keratoderma and neuromuscular abnormality (hind-limb clasping) reminiscent of those seen in Slurp1−/− mice." (PMID 27098205, 2016). "We performed mutational analysis by direct sequencing of SLURP-1 gene in order to identify the genetic defect in three unrelated families (families MDM-12, MDM-13, and MDM-14) variably affected with transgressive palmoplantar keratoderma." (PMID 24093092, 2013). "SLURP1 has been found to be over-expressed in patients with Mal de Meleda, which is a rare autosomal recessive palmoplantar keratoderma." (PMID 21779339, 2011).
mal de Meleda (9 papers, 2015 to 2025). Mal de Melada (MdM) is a diffuse palmoplantar keratoderma initially reported from of the Island of Meleda characterized by symmetric palmoplantar hyperkeratosis that progressively extends to the dorsal surfaces of hands and feet (transgradiens). "Several of the missense mutations in SLURP-1 associated with mal de Meleda affect one of the 10 plesiotypic LU-domain cysteine residues (pCys77Arg, pCys94Ser, and pCys99Tyr)." (PMID 31195646, 2019). "The deficiency and mutations in human SLURP1 gene causes Mal de Meleda (MDM), a rare autosomal recessive genetic disease, characterized by inflammatory palmoplantar keratoderma." (PMID 31068932, 2019). "Mutations or deletions in SLURP1 cause autosomal recessive palmoplantar hyperkeratotic disorder ‘mal de Meleda’." (PMID 27098205, 2016). "SLURP1 is the causal gene for Mal de Meleda (MDM), an autosomal recessive skin disorder characterized by diffuse palmoplantar keratoderma and transgressive keratosis." (PMID 26474319, 2015). "So far 20 mutations in SLURP1 are reported to cause Mal de Meleda, a form of PPK." (PMID 31443639, 2019). "To the best of our knowledge, we believe that SLURP1 may act as a positive modulator, because mutations in SLURP1 cause Mal de Meleda (an inflammatory palmoplantar hyperkeratosis), and α7 nAChR plays a central role in the differentiation of stratified squamous epithelium." (PMID 34721415, 2021).
melanoma (7 papers, 2020 to 2024). A malignant, usually aggressive tumor composed of atypical, neoplastic melanocytes. "In esophageal squamous cell carcinoma, colorectal cancer, melanoma, and lung cancer, the expression of SLURP1 is notably downregulated and is associated with disease staging." (PMID 38686195, 2024). "Furthermore, mutations in SLURP1 can increase the incidence of melanoma and mucosal skin cancer." (PMID 34631779, 2021). "SLURP-1 expression is downregulated in primary and metastatic melanomas compared to normal cells, while elevated plasma level of SLURP-1 correlates with better survival prognosis for patients with pancreatic cancer." (PMID 37854069, 2023). "SLURP-1 expression is down-regulated in primary and metastatic melanomas compared with normal cells, moreover the elevated level of SLURP-1 in plasma correlates with a better survival prognosis for pancreatic cancer patients." (PMID 34595181, 2021). "SLURP-1 expression is down-regulated in primary melanomas and to more extent in metastatic melanomas compared to normal cells." (PMID 33019770, 2020). "Moreover, SLURP-1 was found to antagonize biological functions attributed to Chrna7 in patients with pancreatic cancer or malignant melanoma." (PMID 33815383, 2021).
pancreatic cancer (6 papers, 2018 to 2023). "Further studies are required to understand the role of SLURP1 mRNA and protein in pancreatic cancer and its association with OS outcome in PDAC." (PMID 33613843, 2021). "We observed that increased mRNA of SLURP1 was associated with lower OS outcome in pancreatic cancer." (PMID 33613843, 2021). "A higher level of SLURP1 was associated with a better grade of histological differentiation, but by multivariable analysis emerged as a parameter independently associated with prolonged survival in the patients with resected pancreatic tumors." (PMID 29545933, 2018). "In order to function as an inborn anti-PDAC mechanism, circulating SLURP1 should bind CHRNA7 on pancreatic tumor cells and exert an anti-tumor effect." (PMID 29545933, 2018). "SLURP1 is related to the occurrence and development of pancreatic cancer." (PMID 34631779, 2021). "In line with this, SLURP-1 has been shown to inhibit migration of pancreatic cancer cells." (PMID 34595181, 2021). "Boosting SLURP1-CHRNA7 interaction might represent a novel strategy for treatment in high-risk individuals, i.e., smokers with pancreatic cancer." (PMID 29545933, 2018). "Therefore, we sought to determine whether SLURP1 exerts tumor-suppressive activity in pancreatic cancer cells and, as an endogenous CHRNA7 ligand, is able to block the tumor-promoting effects of nicotine in PDAC." (PMID 29545933, 2018). "However this has not been tested in tumor models, it is plausible that SLURP1 can contribute to pancreatic cancer’s immunosuppressive tumor microenvironment and suppress anti-tumor immune responses." (PMID 33613843, 2021). "To substantiate our claim of SLURP1 having pathobiological relevance because of endocrine-like impact on CHRNA7-positive pancreatic lesions, we attempted to establish a connection between the level of SLURP1 in serum and the molecular landscape of pancreatic tumors." (PMID 29545933, 2018). "The anti-SLURP1 antibody stained esophageal but not pancreatic tissue sections (data not shown), indicating that SLURP1 mRNA-expressing cells might be an extremely rare event in a fraction of pancreatic tumors." (PMID 29545933, 2018).
breast carcinoma (5 papers, 2014 to 2025). "SLURP1 expression was the highest in Basal and Her2+ forms of the four breast cancer subtypes in both METABRIC and TCGA datasets." (PMID 40568095, 2025). "Methylated SYDE1 was demonstrated to be significantly associated with the relapse-free survival of patients with breast cancer However, there are currently no studies regarding the implications of SLURP1 and SYDE2 in cervical cancer." (PMID 25109897, 2014). "The inverse correlation of combined expression of SLURP1 and negatively weighted TGFBR2 with decreased survival was also found in other breast cancer datasets even without deconvolution or the cell identification within the TME." (PMID 40568095, 2025).
colorectal adenocarcinoma (4 papers, 2014 to 2023). The most common type of colorectal carcinoma. "Recently, SLURP-1 expression was detected in HT-29 human colorectal adenocarcinoma cells, and the SLURP-1 expression level in these cells was significantly suppressed upon nicotine treatment." (PMID 26905431, 2016).
colorectal cancer (4 papers, 2019 to 2025). A primary or metastatic malignant neoplasm that affects the colon or rectum. "With these perspectives, SLURP1 could have therapeutic implications for managing inflammation in colorectal cancer." (PMID 37896222, 2023). "The current findings related to SLURP1 antagonizing α7-nAChR could have significant implications for alleviating colorectal cancer by reducing the inflammatory responses." (PMID 37896222, 2023). "Thus, as an autocrine/paracrine signaling molecule, SLURP1 could hold future therapeutic applications in colorectal cancer." (PMID 37896222, 2023).
lung carcinoma (4 papers, 2021 to 2025). "This inverse correlation of high SLURP1 expression with patient survival was also found in lung cancer and myeloma patients in TCGA datasets (Supple fig." (PMID 40568095, 2025). "Conclusively, members of the Ly6/uPAR family such as Lnyx1 or SLURP-1, including their synthetic analogues, are promising options for therapeutically targeting lung cancer or asthma." (PMID 34684676, 2021). "Interestingly, SLURP-1 seems to have protective effects in lung cancer, as it abolishes the proliferation of A549 cells, prevents the downregulation of PTEN expression, an important tumor suppressor, as well as the up-regulation of α7 nAChR expression." (PMID 34684676, 2021). "Besides SLURP-1, lung cancer cells express Lynx1,–another Ly6/uPAR protein, also involved in control of their growth." (PMID 34595181, 2021). "In summary, antiproliferative activity of SLURP-1 in lung cancer cells is mainly mediated by interaction with α7-nAChR, which is realized by means of loop I. However, other molecular targets, e.g., EGFR and PDGFR, are involved in control of lung cancer cell migration by SLURP-1." (PMID 34595181, 2021).
psoriasis (4 papers, 2015 to 2024). An autoimmune condition characterized by red, well-delineated plaques with silvery scales that are usually on the extensor surfaces and scalp. "Because IL-22 induces production of antimicrobial proteins in epithelial cells, the antibacterial activity of SLURP1 was assessed against Staphylococcus aureus (S. aureus), which is known to be associated with disease severity in psoriasis." (PMID 26474319, 2015). "They proposed that this upregulation was likely mediated through the IL22-STAT3 signalling pathway, suggesting a potential role of SLURP1 in psoriasis development." (PMID 38399624, 2024). "Conversely, in psoriasis lesions, the expression of SLURP1 is elevated compared to that in healthy individuals, potentially indicating its role in regulating the proliferation and differentiation of keratinocytes." (PMID 38686195, 2024). "Within the psoriasis-like skin lesions, SLURP1 protein expression was significantly increased in hyperproliferative keratinocytes, and quantitative real-time PCR revealed corresponding elevation of SLURP1 mRNA expression." (PMID 26474319, 2015). "Our aim was to examine the involvement of SLURP1 in the pathophysiology of psoriasis using an imiquimod (IMQ)-induced psoriasis model mice and normal human epidermal keratinocytes (NHEKs)." (PMID 26474319, 2015). "The increased expression of SLURP1 in hyperproliferative keratinocytes within psoriatic lesions is consistent with the increased turnover of the epidermis in psoriasis because SLURP1 accelerates differentiation and apoptosis in keratinocytes." (PMID 26474319, 2015). "In the present study, we explored the involvement of SLURP1 in the pathophysiology of psoriasis using imiquimod (IMQ)-induced psoriatic model mice and normal human epidermal keratinocytes (NHEKs)." (PMID 26474319, 2015). "SLURP1 expression was up-regulated in the skin of IMQ-induced psoriasis model mice." (PMID 26474319, 2015).
atopic dermatitis (3 papers, 2015 to 2024). "Individuals with a mutation that disrupts SLURP-1 function suffer from Mal de Meleda, a transgressive and progressive palmoplantar inflammatory disease resembling the effects of MC hyperactivation in atopic dermatitis." (PMID 33815383, 2021). "We studied MCPs and Chrna7/SLURP1 and their interplay in a mouse model for noise induced stress (NiS) and atopic dermatitis-like allergic inflammation (AlD) and in cultured MC lacking Chrna7." (PMID 38891925, 2024).
colon cancer (3 papers, 2018 to 2025). "The activity of SLURP1 on colon cancer cells was essential to have the function of divalent cations, especially Ca2+ ions." (PMID 37896222, 2023). "Hence, it is pragmatic to investigate the protective functions of SLURP1 on colon cancer cell lines, to establish a plausible link between a reduction in inflammatory responses and cancer cell proliferation." (PMID 37896222, 2023). "Furthermore, the expression of SLURP1 and its modulation in human colon cancer can control the state of the tumor." (PMID 37896222, 2023). "Therefore, exploring SLURP1’s impact on colon cancer proliferation and anti-inflammatory effects could broaden its therapeutic applications." (PMID 37896222, 2023). "Whereas the anti-migratory effect of SLURP1 in PDAC cultures was comparable to that in keratinocytes, the anti-proliferative effect shown for colon cancer cells and keratinocytes was missing." (PMID 29545933, 2018). "Receptor targets of SLURP1, such as α7-nAChRs, Plasminogen Activator, Urokinase Receptor (PLAUR), Plasminogen Activator, Urokinase (PLU), and choline acetyltransferases are significantly expressed in primary colon tumors." (PMID 37896222, 2023).
prostate carcinoma (3 papers, 2019 to 2024). A carcinoma that arises from epithelial cells of the prostate gland. "We will explore the relationship between various stages of prostate cancer pathology and the SLURP1 protein expression." (PMID 38686195, 2024).
bladder cancer (2 papers, 2020 to 2025). "A total of 199 plasma proteins were found to be significantly associated with bladder cancer risk, among which five proteins (SLURP1, LY6D, WFDC1, NOV, and GSTM3) emerged as core candidate targets." (PMID 40740240, 2025). "In summary, through a proteome-wide large-scale two-sample MR analysis combined with colocalization analysis, we identified SLURP1, LY6D, WFDC1, NOV, and GSTM3 as potential plasma proteins associated with bladder cancer." (PMID 40740240, 2025). "Subsequent colocalization analysis highlighted SLURP1, LY6D, WFDC1, NOV, and GSTM3 as being closely linked to bladder cancer occurrence." (PMID 40740240, 2025). "NF-κB is a crucial regulator of cell proliferation and survival, and through this pathway SLURP1 may contribute to the anti-apoptotic and proliferative processes in bladder cancer cells." (PMID 40740240, 2025). "The colocalization analysis revealed that, among the 115 plasma proteins associated in the Olink dataset, three proteins - SLURP1, LY6D, and WFDC1 - exhibited strong evidence of colocalization with bladder cancer risk loci (PP.H3+PP.H4 values ~0.9999, 0.9998, and 0.758, respectively)." (PMID 40740240, 2025). "For instance, SLURP1 has been shown to reduce TNF-α-induced NF-κB activation, thereby suppressing inflammatory responses an anti-inflammatory function that might be important in the bladder cancer microenvironment and SLURP1 can also stabilize epithelial cell junctions." (PMID 40740240, 2025). "Taken together, SLURP1 and LY6D likely contribute to bladder cancer through indirect effects on the tumor microenvironment and immune regulation." (PMID 40740240, 2025). "On the other hand, our findings indicate that the genes SLURP1, LY6D, and WFDC1 may influence bladder cancer development through more indirect or context-specific pathways, rather than through direct causal mechanisms detectable by MR alone." (PMID 40740240, 2025). "SLURP1 and LY6D both belong to the lymphocyte antigen 6 (Ly6) superfamily, which typically play roles in immune responses, and they may influence the tumor microenvironment by modulating immune evasion mechanisms of bladder cancer cells." (PMID 40740240, 2025).